CD4 (CD4 molecule)
Diseases named in the same sentence as CD4 in open-access papers (continued):
Sharing a sentence is not in itself a finding about the gene and the disease.
Autoimmunity (continued). "In autoimmunity and progressive thyroid dysfunction, the rearrangement of N-glycans in Th cells was observed, in opposite directions in the CD4+ pools." (PMID 41030447, 2025). "Regulatory T cells (Tregs) are the aspects of CD4+, and form the central part of the immune regulation; Tregs are crucial for preventing autoimmunity by reducing the intensity of immune responses." (PMID 39996755, 2025). "Memory CD4+T cells are a critical component of the adaptive immune system and drivers of autoimmunity and chronic inflammation." (PMID 40762106, 2025). "Tregs were discovered in the 1990s and are a specialized subset of a cluster of differentiation 4 (CD4) T cells recognized to be constitutionally pivotal for immunologic tolerance and autoimmunity suppression." (PMID 39996755, 2025). "These activated FLS enhance CD4+ T cell activation via antigen presentation and contribute to the maintenance of chronic inflammation and autoimmunity in RA." (PMID 41010616, 2025). "This suggests a distinct modification of CD4 T cells depending on their tissue environment and type of antigen reactivity (virus response, cancer, and autoimmunity)." (PMID 39880819, 2025). "These functions include the differentiation of CD4+ T cells into Treg cells and their activation, making this enzyme an important player in autoimmunity and antitumor immune response." (PMID 40387573, 2025). "Regulatory T cells (Tregs) are a subset of CD4+ T cells that maintain immune tolerance and prevent autoimmunity." (PMID 41480362, 2025). "The pro‐inflammatory action of leptin is reflected in the dysregulation of the CD4+ T cell subset in many autoimmune disorders, which includes increased Th1 and Th17 responses and reduced Treg responses." (PMID 40976999, 2025). "Tregs are a specialized subset of CD4+ T cells that play a crucial role in maintaining immune homeostasis by suppressing excessive immune responses and preventing autoimmunity." (PMID 40901204, 2025). "The molecular pathways through which islet antigen‐specific CD4+ T‐cell populations suppress CD8+ T cells specific for other islet antigens to prevent autoimmunity are not fully understood." (PMID 40623940, 2025). "CD4+ memory T cells and Th2 cells aid in promoting and coordinating immune responses, while regulatory T cells maintain immune homeostasis and prevent autoimmunity." (PMID 40869277, 2025). "It has been shown that IL-6 can strongly inhibit the TGFβ-mediated differentiation of naïve CD4 T cells into regulatory T cells, which inhibit autoimmunity and protect against tissue injury." (PMID 40649269, 2025). "The present study is a continuation of our previous analyses of HT serum proteins, including IgG, and GD Th cells, and focuses on the N-linked glycosylation of CD4+CD25- and CD4+CD25+ T cells in HT autoimmunity." (PMID 41030447, 2025). "This emerging view of clonal adaptation offers key insights into how CD4+ T cells sustain immune surveillance, contribute to disease persistence, and respond to therapies across cancer, infection, and autoimmunity." (PMID 40634636, 2025). "Collectively, these studies highlight the essential role of stem-like CD4+ T cells in sustaining Th1 responses in autoimmunity." (PMID 40634636, 2025). "CD122highLy49+CD8+Tregs are more potent immunoregulatory cells than CD4+Foxp3+T cells to protect from autoimmunity and GVHD." (PMID 41009359, 2025). "The up-regulated MGAT5 expression in both HT1 and HT2 groups vs. CTR and the higher content of complex-type N-glycans in HT1 suggest the importance of branched glycans in the CD25+ pool of CD4+ cells during the early stage of autoimmunization." (PMID 41030447, 2025). "Tregs are a specialized subset of CD4+ T cells that play a pivotal role in maintaining immune tolerance and preventing autoimmunity." (PMID 40901204, 2025).
Autoimmunity (continued). "TAMG also features an imbalance in CD4+ T-cell subsets, with increased Th17 cells and decreased Tregs, driven by elevated levels of IL-6 and IL-21, which further sustain inflammation and autoimmunity." (PMID 41008338, 2025). "These cells have an exhausted phenotype and transcriptional signature that overlap with CD4 T cells in damaged tissues during autoimmunity." (PMID 39880819, 2025). "Several studies have shown the importance of CD4 + CD25 + Foxp3 + Tregs in restraining autoimmunity in T1D." (PMID 39738937, 2025). "These regulatory CD4+ T cells have been recognized as a crucial mechanism in regulating autoimmunity within both mouse and human immune systems." (PMID 40040961, 2025). "Chronic depletion of CD4+ T cells leads to impaired adaptive immune responses, thereby limiting the autoreactive lymphocyte activity that drives autoimmunity." (PMID 41267039, 2025). "In both autoimmunity and alloimmunity, self- or alloantigen-specific stem-like CD4+ cells serve as long-lived reservoirs that continually give rise to pathogenic effector populations." (PMID 40634636, 2025). "Regulatory T cells (Tregs) are a distinctive subset of CD4+ T cells critical in self-tolerance maintenance to prevent the development of autoimmunity." (PMID 41226379, 2025). "These self-proteins are presented as citrullinated peptides by dendritic cell HLA-DR SE molecules, inducing the activation of naïve CD4+ T cells, thereby initiating autoimmunity." (PMID 41010616, 2025). "The association of LoHLAD with pediatric-onset autoimmune rheumatic disease was observed in both HLA-class I and HLA-class II loci but was most notable in class II loci highlighting the prominent role of CD4+ T cells in autoimmunity." (PMID 39941587, 2025). "Conversely, in autoimmunity, transplantation, and allergies, CD4+ T-cell responses often persist despite the presence of regulatory mechanisms." (PMID 40634636, 2025). "IFI30 gene encodes GILT enzyme which is expressed in antigen-presenting cells and plays a role in MHC class II-restricted antigen processing and regulates CD4 + T cell-mediated autoimmunity." (PMID 39992598, 2025). "In human studies, circulating Tfh cells, a subset of CXCR5+Bcl6+ CD4+ T cells in the blood, serve as biomarkers for immune responses, including vaccine efficacy, autoimmunity, and infections." (PMID 40634636, 2025). "CD4+ regulatory T cells (Tregs) expressing the transcription factor Foxp3 play an essential role in immune homeostasis by preventing autoimmunity against self-antigens and curtailing deleterious immune responses toward environmental antigens." (PMID 40762956, 2025). "Tregs are a specialized subset of CD4+ T cells critical for maintaining immune homeostasis, preventing autoimmunity, and modulating immune responses." (PMID 40137319, 2025). "This is consistent with CD3 on HLA DR+ T-cells and CD3 on HLA DR+ CD4+ T-cells which we found, providing evidence of T-cell-mediated autoimmunity." (PMID 39544989, 2024). "The presence of persistent SARS-CoV-2 viral antigens, reactivation of latent viral infections, autoimmunity, dysbiosis, tissue damage and resultant chronic inflammation seen in long COVID implies skewed T-helper-2-cell CD4+ T cell activation." (PMID 38641607, 2024). "Previous studies have linked decreased CD4+ T cell counts in patients with T2DM to impaired immune tolerance and increased autoimmunity." (PMID 39877357, 2024). "To test this, we applied NMFproj to bulk RNA-seq data of sorted peripheral CD4+ T cell fractions from various autoimmune patients." (PMID 38359792, 2024). "Since the onset of their discovery, it is of common understanding that CD4+ regulatory T lymphocytes, or Tregs, belong to a critical subset of regulatory immune cells preventing autoimmunity." (PMID 38404584, 2024). "As an example, in CD4+ T cells, these two receptors oppose each other in the maintenance of autoimmunity." (PMID 39543125, 2024).
Autoimmunity (continued). "IL-2 serves as the principal growth factor for antigen-activated T lymphocytes, exerting control over autoimmunity through the production of CD4+ and CD25+ to regulate T cells." (PMID 38731261, 2024). "Together, these data showed that the presence of myelin-reactive B cells can exacerbate CNS autoimmunity and tissue damage in CD4+ T cell-driven EAE." (PMID 38926356, 2024). "Myocarditis is an inflammatory disease that is primarily driven by CD4+ T cell-mediated autoimmunity." (PMID 38741130, 2024). "These are identified as CD4+Foxp3+, playing critical roles in the prevention of autoimmunity, the maintenance of immune homeostasis, and the suppression of anti-tumor immune responses." (PMID 38673639, 2024). "In the 2000s, the Th17 cell, a CD4 subset that produces the interleukin (IL)-17 family of cytokines, was shown to play a central role in various autoimmune mouse models, including autoimmune arthritis and autoimmune encephalomyelitis." (PMID 37788648, 2024). "NFKB1, known for its role in immune modulation and inflammation, was specifically active in Regulatory CD4+ T Cells, suggesting its contribution to immune tolerance and the prevention of autoimmunity in this subtype." (PMID 39877357, 2024). "Our study presents a hitherto undefined connection between BvCR, BRG1/SWI complex and survivin in CD4+T cells to assure the promotion of DNA damage response ubiquitous in autoimmunity." (PMID 39261837, 2024). "B cells enhance immune response in autoimmunity by producing autoantibody producing plasma cells and promoting CD4+ T cell responses." (PMID 38380335, 2024). "According to the autoimmunity theory of AA, the infiltration of lymphocytes with CD4+, CD8+ T cells, and Natural killer cells was found in a biopsy specimen of affected hair follicles of AA patients." (PMID 39337081, 2024). "Regulatory T cells are a unique subpopulation of CD4+ T cells with immunosuppressive activity that prevents inflammatory injury by inhibiting autoimmunity and regulating the immune response." (PMID 37435641, 2024). "Found in many publications, the canonical introductory sentence illustrates the current view: “CD4+ Tregs is a critical regulatory cell subset maintaining self-reactivity at bay as depletion of Tregs results in autoimmunity and graft rejection”." (PMID 38404584, 2024). "The reasoning behind this was that Sin3a deletion from both suppressive and effector CD4+ T lineages would rescue the severe early-onset autoimmunity and fatality of Sin3a−/−FoxP3cre deletion." (PMID 39156895, 2024). "Research has shown that short-chain fatty acids (SCFAs) can prompt naive CD4 T-cells to develop into Treg cells, offering a viable option for managing autoimmune conditions." (PMID 39606629, 2024). "Cohort survival was consistent with a cohort treated with low-dose IL-2, a CD4 Treg-directed immune therapy used clinically to treat patients with steroid-refractory GvHD or autoimmunity." (PMID 39559361, 2024). "Autoimmune disorders are prevalent due to the failure of regulatory T cells to suppress autologous CD4+ effector T cells." (PMID 39314582, 2024). "Th17 cells, a subpopulation of CD4+ T cells, are involved in coordinating host defense and inflammatory responses in autoimmunity, with BATF binding to the promoters of genes related to Th17 differentiation, including IL-17, IL-21, and IL-22." (PMID 38786064, 2024). "A study using whole-genome sequencing reported that a missense mutation in the Rab44 gene was found in T cells from patients with the autoimmune CD4-lymphoproliferative disease." (PMID 39595070, 2024). "Prior to the onset of autoimmunity, mTORC1 was activated in CD4+ and CD8+ T cells of 20-week-old B6.TC/Rab4AQ72L mice relative to B6/Rab4AQ72L controls." (PMID 38519468, 2024).
Autoimmunity (continued). "Conditional deletion of Mettl3 or Mettl14 in murine CD4+ T cells impairs T cell differentiation and homeostasis, while mice lacking Mettl3 or Mettl14 specifically in Treg cells displayed severe autoimmunity despite normal numbers of Foxp3+ Treg cells." (PMID 37307819, 2024). "Foxp3-expressing CD4 regulatory T (Treg) cells play a crucial role in suppressing autoimmunity, tolerating food antigens and commensal microbiota, and maintaining tissue integrity." (PMID 39882241, 2024). "Autoreactive memory CD4+ T cells showed a pro-inflammatory cytotoxic TH1-like phenotype and expressed genes previously associated with autoimmunity." (PMID 38233524, 2024). "This suggests that Rab4A-mediated mTOR activation is a driver of autoimmunity via expansion of CD4+ over CD8+ T cells in SLE." (PMID 38519468, 2024). "T cells are known to shape immune responses in cancer and mediate autoimmunity, such that CD4+ T helper (Th) and CD8+ T cells mediated effector responses." (PMID 38713284, 2024). "Treg cells, a subset of CD4+ T lymphocytes (1–5% of circulating CD4+ cells), prevent autoimmunity and maintain immune balance." (PMID 39768950, 2024). "Expression of MHCII in neurons will provide insight into the mechanism by which CD4+ T cells contribute to pain, autoimmunity, and neurological diseases." (PMID 38330029, 2024). "In both LT and NLT, Tregs protect against autoimmunity by suppressing responses of CD4+ and CD8+ Tconvs." (PMID 38341270, 2024). "While Th17 is an important cell lineage that propagates autoimmunity, CD4+CD25+FoxP3+ Treg cells inhibit pathological autoimmunity." (PMID 37628811, 2023). "Further, CD39, which is an ectonucleotidase, promotes the accumulation of CD39+CD4+ Tregs in the CNS to suppress autoimmunity." (PMID 37834203, 2023). "Based on the critical role of CD4+ T-cell subsets in autoimmunity, targeting CD4+ T-cell subsets seems to be a potential therapeutic approach for AIH." (PMID 37695088, 2023). "Cytotoxic CD4+ T cells displaying similar features have been described previously in chronic viral infections, cancer and autoimmunity, suggesting that these changes likely result from persistent antigenic stimulation." (PMID 37063893, 2023). "Patients with other monogenic autoimmunity had a similar %TSDR/CD4 to controls (median 8.7%, p = 1.0)." (PMID 36600150, 2023). "CD4+ Foxp3+ regulatory T cells (Tregs) are indispensable for preventing autoimmunity, and they play a role in cancer and transplantation settings by restraining immune responses." (PMID 38993904, 2023). "CD4+Foxp3+T regulatory cells are the key cells to inhibit autoimmunity and maintain autoimmunity tolerance." (PMID 36890410, 2023). "The findings from this study indicate that the FA desaturase SCD1 tightly controls T cell fate and autoimmunity and that its activity is increased in CD4+ T cells of MS patients." (PMID 37041314, 2023). "A recent study also identified a connection between the presence of the TGF inhibitor Smad7 on intestinal CD4+ T cells and autoimmunity in EAE." (PMID 38090441, 2023). "This autoimmunity is characterized by lymphadenopathy, splenomegaly, thymic shrinkage, skin rash, and overwhelming infiltration of CD4+ memory T cells and CD8+ effector T cells into the peripheral tissues." (PMID 38201290, 2023). "Having identified enhanced SCD1 activity in CD4+ cells of MS patients, we next sought to define its impact on autoimmunity." (PMID 37041314, 2023). "Most insights into CD4+ T cells have focused on anti-viral immunity and autoimmunity, such as human cytomegalovirus, epstein-barr virus, and autoimmune encephalomyelitis." (PMID 37063862, 2023). "We also identified several genes highly expressed in Th17 cells, including Id2, which mediates the CD4 + T cells immune response, and Fos, which plays a crucial role in autoimmunity and inflammation." (PMID 37344856, 2023).
Autoimmunity (continued). "Although too little regulatory help leads to allergies and autoimmunity, increased activity of CD4+ Tregs can prevent protective anti-cancer or anti-infection immune responses that can worsen patient survival." (PMID 37892982, 2023). "In the thymus, a restricted number of autoreactive CD4 T-cells differentiate into nTregs, in a process called agonist selection that guarantees central tolerance to self-antigens, thus avoiding autoimmunity." (PMID 36769019, 2023). "Tregs, a subpopulation of CD4+ T lymphocytes, are essential for maintenance of peripheral immunological tolerance and prevention of autoimmunity, and have received extensive attention in the field of neuroinflammation in recent years." (PMID 36650518, 2023). "Their study noted that T cell receptor (TCR) cross-reactivity between MHC Class II-binding self and foreign peptides appeared to influence naive CD4+ T cell repertoire and autoimmunity." (PMID 37766162, 2023). "Collectively, mitochondrial Tfam in CD4+ T cells governs mitochondrial fitness, the balance between effector and regulatory T cells, and autoimmunity." (PMID 37809060, 2023). "T helper 17 (Th17) cells are a subset of CD4+ T helper cells involved in the inflammatory response in autoimmunity." (PMID 36792629, 2023). "T cells, especially CD4 + T cells, are the main drivers of heart-specific autoimmunity in myocarditis." (PMID 36436002, 2023). "CD4+ Treg cells are a subset of T cells with the capacity to negatively regulate the immune response, maintaining homeostasis and preventing autoimmunity." (PMID 36987861, 2023). "Human Th17 cells phenotypically resemble memory T cells in autoimmunity and antitumor response and show higher capacity for proliferative self-renewal and plasticity to interconvert into other CD4+ T cell subsets." (PMID 37384407, 2023). "In this regard, activation of CD56bright NK cells can suppress activated autologous CD4+ T cells and subsequently prevent the initiation of autoimmunity." (PMID 37275764, 2023). "One of the important CD4+ helper T-cell functions is that of regulatory T (Treg) cells, which are regulators of immune responses pertaining to tolerance, autoimmunity, and anti-tumor immunity." (PMID 38201290, 2023). "CD4-CTLs have emerged as significant mediators of immunity during infection, anti-tumor responses, and autoimmunity." (PMID 36964178, 2023). "In fact, it is known that T cells, including CD4+ and CD8+, have an important antiviral role in balancing the response against pathogens and the risk of developing autoimmunity or excessive inflammation." (PMID 37035317, 2023). "Lactic acid bacteria have been shown to prevent intestinal inflammation and autoimmunity by increasing IL-10 and CD4+ CD25+ Treg cells." (PMID 37894114, 2023). "Here we explore T1D case-control differences in splicing focusing on a subset of CD4+ T cells with particular relevance to autoimmunity." (PMID 37758901, 2023). "In particular, regulation of CD4+ T-cell differentiation is essential to maintain an optimal balance of CD4+ T-cell subsets to support immune homeostasis and prevent autoimmunity." (PMID 36678126, 2023). "cMaf was also reported to be important for the induction of CD4+ T cell-produced IL-10, which is required to suppress Th1-, Th2-, and Th17-mediated pathology in experimental models of malaria, allergy, and autoimmunity, respectively." (PMID 36594463, 2023). "The autoimmunity found in T1D is mediated by CD4+ T cells, which are involved in M1 macrophage activation and the recruitment of CD8+ cytotoxic T cells." (PMID 37400916, 2023). "Specifically, there is a notorious reduction in IL-2 (essential for maintaining regulatory function) and enhanced IL-17 production (a critical cytokine in promoting autoimmunity), as seen in CD4+ Tconv cells from patients and in animal models." (PMID 38203623, 2023).